PHF13 (PHD finger protein 13)
Description:
Modulates chromatin structure and DNA damage response by regulating key determinants of chromatin compaction and DNA damage response. Binds H3K4me3-containing chromatin and promotes DNA condensation by recruiting corepressors such as TRIM28 and H3K9 methyltransferase SETDB1. Required for normal chromosome condensation during the early stages of mitosis. Required for normal chromosome separation during mitosis. Increases both chromatin-associated levels and activity of H3K9 methyltransferases, such as SETDB1, thus enhancing H3K9 trimethylation. Essential for testicular stem-cell differentiation and sustained spermatogenesis (By similarity).
Synonyms: SPOC1; MGC43399; PHF5
Tractability: PROTAC: ubiquitination databases record sites on it.
Target class: Plant homeodomain; Epigenetic regulator; Reader
Gene: Protein-coding gene on chromosome 1 (6,613,731 to 6,624,030, forward strand). Ensembl gene ENSG00000116273.
Subcellular location: Nucleus; Nucleus, nucleoplasm
Gene Ontology:
Molecular function: chromatin binding; chromatin-protein adaptor activity; histone H3K9me2/3 reader activity; protein binding
Biological process: chromosome segregation; DNA damage response; mitotic cell cycle; mitotic chromosome condensation; chromatin organization
Cellular component: nucleus; nucleoplasm
Genetic constraint (gnomAD): Loss-of-function variants: 1 observed, 25.87 expected, observed/expected ratio (o/e) 0.0387, 90% interval 0.013 to 0.18. The upper end of that interval is the gene's LOEUF score, 0.18, which puts it in group 1 of 6, group 1 being the genes least tolerant of losing a copy. Missense variants: 306 observed, 421.92 expected, observed/expected ratio (o/e) 0.73, 90% interval 0.66 to 0.8. Synonymous variants: 195 observed, 170.8 expected, observed/expected ratio (o/e) 1.14, 90% interval 1.01 to 1.29.
Homologues: Orthologues: chimpanzee PHF13 (100% identical), dog PHF13 (96% identical), macaque PHF13 (96% identical), mouse Phf13 (92% identical), pig PHF13 (90% identical), rat Phf13 (90% identical), rabbit PHF13 (90% identical), guinea pig PHF13 (89% identical), tropical clawed frog phf13 (63% identical), zebrafish phf13 (56% identical). Paralogues in human: PHF23 (38% identical).
Diseases named in the same sentence as PHF13 in open-access papers:
PHF13 is named in the same sentence as 19 diseases in open-access papers, as found by Europe PMC text mining. Sharing a sentence is not in itself a finding about the gene and the disease. The quoted sentences say what the papers report.
ovarian carcinoma (5 papers, 2012 to 2024). A malignant neoplasm originating from the surface ovarian epithelium. "A number of RFs against various viruses are known; among them is the cellular protein SPOC1 (survival time-associated PHD (plant homeodomain) in ovarian cancer 1), also called PHF13 (PHD finger 13)." (PMID 38543731, 2024). "SPOC1 (survival-time associated PHD protein in ovarian cancer 1), also known as PHF13 (PHD finger 13), was first described in 2005 as a novel cellular protein with a single plant homeodomain (PHD) showing high expression in ovarian carcinoma patients which correlated with poor prognosis." (PMID 33530304, 2021).
HIV-1 infection (3 papers, 2017 to 2024). The type species of lentivirus and the etiologic agent of acquired immunodeficiency syndrome (AIDS). "We therefore investigated the role of PHF13 during HIV-1 infection and found that the expression of PHF13 is tightly regulated throughout the viral replication cycle." (PMID 29021215, 2017). "This analysis revealed that PHF13 overexpression prior to HIV-1 infection leads to a higher number of integrated proviral genomes; in U2OS-C5 cells up to threefold and in Jurkat T cells with approximately eightfold increased efficiency." (PMID 29021215, 2017). "To analyse at which stage of the HIV-1 infection cycle PHF13 degradation occurs, we used different inhibitors targeting specific steps of viral replication." (PMID 29021215, 2017). "Conversely, knockdown of PHF13 in ΔVpr HIV-1 infections led to a complete recovery of viral gene expression similar to HIV-1 WT." (PMID 29021215, 2017). "The same was true for CD4+ Jurkat cells, which were electroporated to express PHF13, such that in BFP-positive cells, which overexpressed PHF13, HIV-1 infection was roughly twofold more efficient when compared with Jurkat cells electroporated with a BFP-only control plasmid." (PMID 29021215, 2017). "We next measured the dynamics of PHF13 reduction upon HIV-1 infection." (PMID 29021215, 2017). "PHF13 overexpression was induced in U2OS-C5 cells and 24 h later cells were infected with HIV-1 NL4-3 GFP, allowing for quantitation of HIV-1 infection by measuring the percentage of GFP-expressing cells." (PMID 29021215, 2017). "Altogether, oppositely what we expected, PHF13 has positive as well as negative effects on viral replication dependent on the stage of HIV-1 infection." (PMID 29021215, 2017).
pancreatic cancer (3 papers, 2022 to 2025). "For instance, PHD finger protein 13 (PHF13) induces increased deposition of the activating epigenetic marks H3K4me3 on genes critical to pancreatic cancer cell migration and invasion." (PMID 37370109, 2023). "To confirm the findings in vitro, we analyzed the public available RNA-seq data of human pancreatic cancers to identify the differential expressed genes between PHF13 highly and lowly expressed pancreatic cancers." (PMID 35597793, 2022). "In this study, we demonstrate that PHF13 is required for pancreatic-cancer-cell growth and metastasis." (PMID 35597793, 2022). "Together, these findings suggest a novel epigenetic mechanism of PHF13 in promoting cancer-cell migration and identify PHF13 as a potential therapeutic target for human pancreatic cancer." (PMID 35597793, 2022). "The expression of PHF13 was also significantly higher in pancreatic cancer with metastases in axillary lymph nodes." (PMID 35597793, 2022). "Together, these results demonstrate the correlation between PHF13 expression and patient outcomes, indicating a potential oncogenic role for PHF13 in pancreatic cancer." (PMID 35597793, 2022). "To understand the role of PHF13 in pancreatic cancer, we investigated its expression pattern in human tumors, compared with normal tissues, and found an elevated expression of PHF13 in pancreatic adenocarcinoma." (PMID 35597793, 2022). "To determine the role of PHF13 in human pancreatic cancers, we performed mRNA-seq upon siRNA-mediated depletion of PHF13 in Panc-1." (PMID 35597793, 2022). "Here, we showed that PHF13, a newly identified epigenetic reader of H3K4me2/3, is highly expressed in human pancreatic tumors characterized by metastasis." (PMID 35597793, 2022). "Moreover, weighted gene co-expression network analysis (WGCNA) was performed to determine the correlations between the expression of PHF13 and the subtypes of pancreatic cancers." (PMID 35597793, 2022). "In addition, PHF13 showed much higher expression in the basal-like subtype of pancreatic cancer that is characterized by aggressive activity, undifferentiated histopathology, and worse prognosis, compared to the classical subtype." (PMID 35597793, 2022). "Thus, in vitro and in vivo data provide further support for the role of PHF13 in controlling pancreatic-cancer-cell proliferation." (PMID 35597793, 2022). "Moreover, the preferentially expressed genes in the most aggressive SQ subtype of pancreatic cancers were negatively enriched in PHF13-depleted cells." (PMID 35597793, 2022). "Moreover, highly expressed PHF13 was significantly correlated with high-grade pancreatic cancer." (PMID 35597793, 2022). "Though its function is not known in leukemia and lymphoma, PHF13 regulates genes critical for pancreatic cancer cell migration and invasion." (PMID 40282457, 2025).
pancreas ductal adenocarcinoma (1 paper, 2022). "Utilizing a cell culture-based approach, we provide evidence that depletion of PHF13 impaired TGFβ-induced EMT in pancreas ductal adenocarcinoma cell Panc-1." (PMID 35597793, 2022). "In this study, we demonstrate that PHF13-depleted pancreas ductal adenocarcinoma cells Panc-1 show a significantly decreased cell proliferation in vitro and in vivo." (PMID 35597793, 2022). "Importantly, Kaplan–Meier analysis demonstrated that high PHF13 expression significantly worsened survival rates in patients with pancreatic ductal adenocarcinoma." (PMID 35597793, 2022).
pancreatic adenocarcinoma (1 paper, 2022). "Interestingly, PHF13 depletion significantly downregulated the targets of KRAS (3G), which is frequently activated in most pancreatic adenocarcinomas and is known to be an essential driver of human cancer." (PMID 35597793, 2022).
systemic lupus erythematosus (1 paper, 2023). An autoimmune multi-organ disease typically associated with vasculopathy and autoantibody production. "The PHF13 low-expression subgroup was significantly enriched in ribosomes and systemic lupus erythematosus." (PMID 37841281, 2023).
infection (6 papers, 2013 to 2024). The state of being infected such as from the introduction of a foreign agent such as serum, vaccine, antigenic substance or organism. "In contrast, infection of 293T cells with VSVG pseudotyped HIV-1 led to a complete loss of PHF13 expression and this phenotype was again clearly attributable to Vpr." (PMID 29021215, 2017). "WT HIV-1-infected SupT1 cells displayed strongly reduced PHF13 levels, and the same was true for infection with Nef- and Vpu-deficient HIV-1." (PMID 29021215, 2017). "PHF13 knockdown in ΔVpr infections led to levels of HIV-1 gene expression and virus release which were comparable to the levels observed with HIV-1 WT." (PMID 29021215, 2017). "This confirmed equal infection efficiencies by p24 detection, the efficiency of siRNA-mediated PHF13 knock-down and PHF13 overexpression when induced with doxycycline, as well as PHF13 degradation by Vpr." (PMID 29021215, 2017). "In contrast to what we observed when PHF13 was overexpressed prior to infection, the total number of HIV-1-infected cells (% GFP+) remained comparable between doxycycline induced and non-induced cells." (PMID 29021215, 2017). "Strikingly, infection with Vpr-deleted HIV-1 (ΔVpr) resulted in PHF13 levels comparable with mock-infected cells." (PMID 29021215, 2017). "From these data we conclude that HIV-1 reduces PHF13 levels early post-infection in a time-dependent manner in virally infected T cells." (PMID 29021215, 2017). "Hence, PHF13 appeared to enhance the number of infected cells when it was expressed prior to infection of target cells, although PHF13 was suggested to act as HIV-1 restriction factor." (PMID 29021215, 2017). "Our recent study using direct imaging approaches for incoming Ad genome complexes showed that neither IFI16 nor PHF13/SPOC1 associates with incoming Ad genomes during immediate early phases of infection." (PMID 27782081, 2016). "As expected, when PHF13 is overexpressed or knocked down at the post-integration step, the total percentage of HIV-1-infected (% GFP+) cells was comparable between all infections." (PMID 29021215, 2017). "We first clarified whether PHF13 is expressed in non-infected cell lines relevant for production and infection of HIV-1 as well as primary target cells (i.e. PBMC, CD4+ T cells and macrophages)." (PMID 29021215, 2017).
cancer (5 papers, 2012 to 2022). A tumor composed of atypical neoplastic, often pleomorphic cells that invade other tissues. "In addition, similar to PML-NB components and IFI16, a host protein PHF13/SPOC1 (survival-time associated PHD finger protein in ovarian cancer 1/PHF13) has been recently suggested as a novel restriction factor targeting incoming Ad genomes, without any support of microscopic evidence." (PMID 27782081, 2016). "Given the essential role of super-enhancers (SEs) in cancer metastasis, we next sought to examine the role of PHF13 in controlling SEs during TGFβ-induced EMT." (PMID 35597793, 2022). "In conclusion, we have provided mechanistic insights to explain the role of PHF13 in cancer metastasis by employing genome-wide analysis to understand its effects on chromatin activity and gene expression during TGFβ-induced EMT." (PMID 35597793, 2022). "Altogether, these findings reveal PHF13 as a novel therapeutic target for human cancers and provide a basis for further investigation of its oncogenic role in various types of human cancer." (PMID 35597793, 2022). "Furthermore, PHF13-dependent chromatin regions are enriched in broad H3K4me3 domains and super-enhancers, which control genes critical to cancer-cell migration and invasion, such as SNAI1 and SOX9." (PMID 35597793, 2022). "Notably, we confirmed this finding in the individual example of PHF13-bound and TGFβ-activated gene SNAI1, whose expression was dependent on PHF13 and highly associated with cancer metastasis." (PMID 35597793, 2022).
tumor (1 paper, 2022). "To confirm the potential role of PHF13 in controlling tumor metastasis, we investigated the influence of PHF13 depletion on TGFβ-induced EMT." (PMID 35597793, 2022).
PHF13 also shares sentences with these, for which no sentence is quoted: adenovirus infection (2 papers); HCMV infection (2); colon carcinoma (1); leukemia (1); lymphoma (1); mild cognitive impairment (1); neuroblastoma (1); osteosarcoma (1); ovarian tumour (1); virus infection (1).